RUNX2 (RUNX family transcription factor 2)
Diseases named in the same sentence as RUNX2 in open-access papers (continued):
Sharing a sentence is not in itself a finding about the gene and the disease.
tumor (continued). "In the last decade, Runx2 has been shown to be involved in the regulation of cancer progression with dual functions of oncogenic potential and tumor suppressor abilities." (PMID 33767130, 2021). "For instance, high expression of Runx2 was significantly correlated with larger tumor size, lymph node metastasis, and shorter postoperative survival time of patients with non-small cell lung cancer." (PMID 33767130, 2021). "In this part of the study, we explored the effects of different Mlt and Zol concentrations on the mRNA and protein expression of osteogenesis markers (OPN, OCN, and RUNX2) in tumor cells." (PMID 34447747, 2021). "ACHN and 786-O cells with knockdown of Runx2 were subcutaneously injected into nude mice, and the tumor volume was measured every week." (PMID 33767130, 2021). "The WNT signaling originated from tumor cells is essential to direct OBL differentiation by activating the transcription factor RUNT-related transcription factor 2 (RUNX2)." (PMID 33869035, 2021). "The responses of tumor cells to osteocyte-derived CM were characterized by the expression of tumorigenic genes such as Runx2, MMP9, TGFβ, and Snail." (PMID 33802279, 2021). "Localization of CD44-ICD and RUNX2 in the nuclei of adenocarcinoma further highlights the potential role of these proteins in transcriptional regulation and tumor progression." (PMID 33062960, 2020). "Survivin was co-expressed with one of this transcriptional regulator Runt-related transcription factor 2 (Runx2) and both showed positive correlation with tumor growth in these CSCs." (PMID 32691369, 2020). "The role of Runx2 in increasing the metastatic potential of tumor cells has been connected with its ability to regulate important genes related to tumor progression such as the vascular endothelial growth factor (VEGF) and osteopontin (OPN)." (PMID 33086487, 2020). "RUNX3 plays an important role in inflammation and tumor suppression, while RUNX2 (CBFA1) has evolved a unique role in bone development and is regarded as the master regulator of osteogenesis." (PMID 33319865, 2020). "The present data showed that RUNX2, a well-known transcription factor that participated in tumor EMT, migration, and invasion, was recognized as the downstream target of miR-204-5p and had a competition with SNHG4 to interact with miR-204-5p in RCC cell lines." (PMID 33088220, 2020). "The ability of RUNX2 to enhance the metastatic potential of tumor cells is largely based on its ability to regulate genes crucial to tumor progression including VEGF, MMP9, MMP13, OPN, SNAI 1–2, TWIST1 and TIMP13." (PMID 31395086, 2019). "In this study, we used MYC/Runx2 mice, a transgenic model displaying rapid tumor formation that is further accelerated by MLV infection." (PMID 31815961, 2019). "Altered RUNX2 function is involved in unchecked pathways promoting tumor progression, EMT, and metastasis." (PMID 31832019, 2019). "Consistent evidence indicates that RUNX2 expression is aberrantly reactivated in cancer and supports tumor progression." (PMID 31395086, 2019). "Knockdown of Runx2 resulted in similar trends of changes in tumor and stem cell phenotypes compared to miR-196a downregulation." (PMID 31614906, 2019). "The RUNX2 gene encodes two major isoforms starting from two alternative promoters, the isoform I, controlled by the proximal P2 promoter, is the major RUNX2 isoform in tumor cells." (PMID 31395086, 2019).
tumor (continued). "To analyze the contribution of HDACs to RUNX2 regulation and the effect of their inhibition in cancer biology, we selected a panel of cell lines derived from tumor types in which RUNX2 has been shown to be involved." (PMID 31395086, 2019). "Runx2 is a lineage-specific transcription factor currently emerges as a key player involved in tumor metastasis." (PMID 30930692, 2019). "This suggests that Runx2-mediated integrin α5 expression within the primary tumor selects cells that are more likely to colonize the bone and have a survival advantage at the secondary site." (PMID 29642534, 2018). "Several reports have shown that the high expressions of Runx-2 are obviously correlated with high histological grade, multiple tumor nodes, and tumor infiltration and metastasis." (PMID 30105080, 2018). "This is associated with the reduced expression of Runt-related transcription factor 2 (RUNX2) and C-X-C motif chemokine 12 (CXCL12) in tumor cells." (PMID 30577536, 2018). "In thyroid cancer patients, we found that RUNX2 mRNA levels were higher in tumor tissue than in normal tissue." (PMID 30463392, 2018). "Recently, the possible involvement of RUNX2 in tumor initiation/progression has been increasingly recognized depending on the cellular context." (PMID 29558908, 2018). "Increased expression of VDR and FGF23 relative to other VRS components is interesting, especially in the context of increased Runx2 expression as previously observed in the same OS-core type, and also in the tumor tissue isolated from the BOOM model." (PMID 28300755, 2017). "Recently, a novel role of Runx2 in tumor cell survival became evident as studies reveal that Runx2 inhibited the apoptotic pathway by activating the expression of survivin and Bcl2." (PMID 28300755, 2017). "Both tumor burden (p < 0.05) and tumor weight (p < 0.001) were reduced by silencing RUNX2 expression." (PMID 28120940, 2017). "Secondly, concordant up-regulation of PTHLH and RUNX2 promoted HNSCC tumor growth, and RUNX2 was stimulated by calcium level." (PMID 28120940, 2017). "Conditional RUNX2 deletion in the MMTV-PyMT transgenic mouse model of BC has been shown to delay tumor incidence and enhance overall survival." (PMID 29050333, 2017). "In other words, over-expression of Runx2 counterbalanced the tumour suppressor effect of miR-302b mimics on cell invasion and migration in 143B cells." (PMID 29042587, 2017). "Evidence is rapidly accruing for the oncogenic and tumor suppressor functions of the Runx family of transcription factors, Runx1, Runx2 and Runx3, which are essential for normal lineage specific development." (PMID 28407681, 2017). "Runx2 expression has a pro-survival role in rapidly proliferating tumor cells in the bone microenvironment by promoting PTH or PTHrP mediated antiapoptototic effect and inducing the expression of survivin." (PMID 28300755, 2017). "We further used the shRUNX2-1 clone to measure the in vivo tumor growth abilities governed by RUNX2." (PMID 28120940, 2017). "In summary, our results reveal that PTHLH expression is a poor prognosis marker in HNSCC patients, and RUNX2-PTHLH axis contributes to HNSCC tumor growth." (PMID 28120940, 2017). "In a TNBC-PDX Br-001 model, RUNX2 expression was positive during continuous passage from P1 to P3, and a significant decrease of tumor volume was observed in the CADD522-injected Br-001-bearing athymic mice (10 mg/kg, i.p)." (PMID 29050333, 2017). "The results show RUNX2 promoted in vitro proliferation abilities (p < 0.001) and in vivo tumor growth (p < 0.05 and 4D, p < 0.001)." (PMID 28120940, 2017).
tumor (continued). "We observed that MMTV-PyMT females developed palpable mammary gland tumors at approximately 5 ∼ 6 weeks of age, and high levels of RUNX2 were expressed in tumor tissues compared to normal mammary gland in age-matched control mice over 10 weeks of observation." (PMID 29050333, 2017). "Abnormally high levels of Runx2, and their targeted genes, in human prostate tissue and cells lines positively correlate with tumor stage and aggressiveness." (PMID 27634876, 2016). "Our study demonstrated that the tumor-promoting activity of RUNX2 was attributable to its transcriptional up-regulation of the chemokine receptor CXCR4, which has been shown to mediate the invasion and metastasis of a variety of cancers." (PMID 27007162, 2016). "As miRNAs directly control Runx expression and are established epigenetic regulators of cancer initiation, tumor progression, and metastasis, we postulate that miRNAs targeting Runx1 and/or Runx2 would have reciprocal expression in TRAMP prostates." (PMID 27634876, 2016). "Runx1 and Runx2 continuously increase while miRNAs with predicted or validated repression of Runx factors decrease during tumor progression." (PMID 27634876, 2016). "Runx2 is a transcription factor involved in bone metabolism and tumor growth, and SPARC is a target gene of Runx2, showing two HRE binding sites in the promoter." (PMID 27187355, 2016). "We further examined the relationship of RUNX2 to the invasiveness and metastasis of human GC cells in a modified orthotopic tumor implantation model, in which genetically engineered GC cells were injected into the stomach subserosa of nude mice." (PMID 27007162, 2016). "Our study provides insight into the pleiotropic regulatory role of transcription factors, e.g., RUNX2 in cell fate determination and the regulation of differentiation during tissue development and tumor progression." (PMID 27806311, 2016). "RUNX2 level was positively correlated tumor invasion depth, lymph node metastasis and TNM status (P < 0.01 for all)." (PMID 27007162, 2016). "The phosphorylation of RUNX2 by AKT, ERK and p38 and the effect of these phosphorylation events on RUNX2 activity have to be contextualized in tumor cells exhibiting continuous cross-talk between the RAS/MAPK and PI3K/AKT pathways." (PMID 26204939, 2015). "An emerging body of evidence suggests that the RUNX2 transcription factor, a key regulator of osteogenesis, can play a role in breast carcinogenesis, particularly in proliferation and metastasis." (PMID 26404249, 2015). "As it appears that two or even the three RUNX proteins are often co-expressed in tumor cells, how does the phosphorylation of RUNX1 and RUNX3 by AKT modulate the effects of AKT-mediated RUNX2 phosphorylation on tumor progression?" (PMID 26204939, 2015). "RUNX2 levels were reported to correlate with a number of clinico-pathological indicators, including tumor stage, histological grade, and HER2 status." (PMID 26404249, 2015). "The function of RUNX2 in early stage luminal BC is not completely understood, although it is known to exhibit either tumor suppressive or oncogenic activity, depending on expression of ER." (PMID 26320173, 2015). "We found that RUNX2 target genes related to tumor properties are significantly downregulated in HOS-WWOX and LM7-WWOX OS cell lines when compared to the EV cells." (PMID 26256646, 2015).
tumor (continued). "Authors have reported that TEADs and RUNX2 play important roles in mediation of TAZ's oncogenic effect on tumor development and progression, especially TEADs, which play predominant roles in TAZ-mediated cancer cell proliferation and EMT." (PMID 26416426, 2015). "In the context of cancer cells where autocrine and paracrine activation of growth factor receptors contribute to tumor progression, RUNX2 undergoes phosphorylation by both ERK and AKT kinases." (PMID 26204939, 2015). "This indirect mechanism of RUNX2 activation by the PI3K/AKT pathway is also described in human tumor cells." (PMID 26204939, 2015). "Signaling crosstalk represents an important component regulating RUNX2 as a driver of tumor progression via phosphorylation." (PMID 26204939, 2015). "In this study, estradiol stimulated cancer cell colonies growth, while RUNX2 inhibited this process, acting as a tumor suppressor." (PMID 26404249, 2015). "RUNX2-high tumours accounted for 13 of 84 (15%) triple-negative cancers in the cohort (P=0.008; chi-square test)." (PMID 24626992, 2014). "The expression levels of RUNX2 and miR-10a/b were determined in tumor tissues and adjacent non-tumor tissues by qPCR." (PMID 25266482, 2014). "Transgenic mice expressing two potent collaborating oncogenes in the germ line (CD2-MYC, -Runx2) develop rapid onset tumours that can be accelerated and rendered polyclonal by neonatal Moloney murine leukaemia virus (MoMLV) infection." (PMID 24586197, 2014). "Compared to MYC/Runx2, the other three tumour sets yielded many more reads, but from a much smaller number of unique RISs, reflecting the presence of highly expanded tumour clones." (PMID 24586197, 2014). "As expected, the Runx genes (Runx2 and Runx3) and Myc family targets (Myc, Mycn) conformed to this pattern, being selected in CD2-MYC and CD2-Runx2 respectively and effectively disappearing from the double transgenic tumours." (PMID 24586197, 2014). "Owing to the small number of RUNX2-positive tumours, these results fail to reach statistical significance and warrant validation in a larger independent cohort." (PMID 24626992, 2014). "The median expression levels of RUNX2 and miR-10b were significantly higher in tumor tissue than in non-tumor tissues by 2.16 and 1.73 fold, respectively (p < 0.0001, p < 0.0001)." (PMID 25266482, 2014). "In epithelial ovarian cancer, various genes involved in tumor invasion and metastasis were suppressed upon RUNX2 knockdown." (PMID 25266482, 2014). "RUNX2 forms complexes with Smad proteins as a requirement for mediating BMP/TGF β responsiveness in tumor cells." (PMID 22966907, 2012). "The aberrations of three selected genes, CXCL5, DLX5 and RUNX2, were validated in five cell lines and five tumour samples using PCR techniques." (PMID 23144859, 2012). "αv integrin signalling controls tumour growth at all stages of disease, and both αv and Runx2 promote metastasis and tumour growth in the bone microenvironment." (PMID 24213501, 2012). "RUNX2 expression in cancer cells facilitates the interaction between tumor cells and the bone microenvironment that lead to osteolytic disease." (PMID 22966907, 2012). "The unavailability of the phospho-RUNX2 antibody prevented us from determining its localization in the normal and tumor prostatic tissue." (PMID 22966907, 2012). "Runx2 is a DNA-binding transcription factor which plays a master role in tumor-induced angiogenesis and cancer cells metastasis by interaction with the TGF-β/Smad pathway of transcriptional modulators." (PMID 21649908, 2011). "Collectively, these results suggest that Runx2 is able to bypass the differentiation defects that are downstream in the cascade from the BMPs, and thus, able to inhibit tumor progression through the induction of osteogenic differentiation." (PMID 21437219, 2011).
tumor (continued). "While early regulators of osteogenesis are unable to bypass these defects, late osteogenic regulators, including Runx2 and Osterix, are able to overcome some of the defects and inhibit tumor propagation through promoting osteogenic differentiation." (PMID 21437219, 2011). "It' well known that this cohort regulated by Runx2 is essential mediators of tumor invasion and metastasis." (PMID 21649908, 2011). "Recent Studies showed that Runx2 mediates endothelial cell migration and invasion during tumor angiogenesis." (PMID 21649908, 2011). "The tumor sample #256 that exhibited the worst response to chemotherapy, also showed highest levels (113-fold) of RUNX2 overexpression." (PMID 20465837, 2010). "In conclusion, Runx2 is upregulated in a subset of PDAC tissues, both in tumour cells and the associated fibroblasts." (PMID 17876328, 2007). "Since SPARC is thought to act as a tumour promoter, these findings point again to Runx2 as a potential tumour suppressor." (PMID 17876328, 2007). "The long CpG islands of the PAX5 and RUNX2 genes neighboring a small number of retroelements at a long distance, > 6 kb, showed insignificant methylation alterations in the tumor tissues." (PMID 16827945, 2006). "This study concludes that RUNX2 is markedly overexpressed in ES tissues and may contribute to tumor advancement, whereas WWOX levels remain stable." (PMID 41141138, 2025). "The RUNX family—RUNX1 (Runt-related transcription factor 1), RUNX2 (Runt-related transcription factor 2), and RUNX3 (Runt-related transcription factor 3)—has been implicated in both normal development and oncogenesis, with RUNX3 functioning as a tumor-suppressor gene across multiple malignancies." (PMID 41181710, 2025). "Moreover, in human GCTb, RUNX2 expression is associated with the upregulation of MMP13, which is the main proteinase expressed by the stromal cell component of the tumor." (PMID 40075982, 2025). "Importantly, a regulatory axis between HEY1-NCOA2 and Runx2 was identified: CRISPR-mediated knockout of Runx2 delayed tumor onset in vivo but resulted in poorly differentiated tumors dominated by small round cells." (PMID 40867318, 2025). "Finally, our findings highlight the potential role of RUNX2 in CD8+CD226+ T cell effector functions positively correlated with tumor‐infiltrating CD8+ T cells." (PMID 39777847, 2025). "Here, WWOX acts as a tumor suppressor by directly interacting with RUNX2." (PMID 41141138, 2025). "Thus, under hypoxic tumour conditions, RUNX2 overexpression enhanced VEGF expression, promoted anti-apoptotic activity, and accelerated tumour progression." (PMID 40806771, 2025). "In addition, Runt-related transcription factor 2 (Runx2) is a key regulator of osteogenic differentiation and tumor invasion in OS." (PMID 40870392, 2025). "We observed a marked increase in apoptosis in BLCA cells following knockdown of FASN or RUNX2, indicating that both genes may promote tumor growth by conferring anti-apoptotic advantages." (PMID 40703521, 2025). "In simpler terms, RUNX2 may act like a “switch” that pushes tumor cells toward a bone-forming, invasive state, and blocking this switch could potentially slow or prevent tumor spread, offering a future therapeutic opportunity." (PMID 41141138, 2025). "RUNX2 plays a critical role in tumor progression and bone metastasis, whereas TGFBI may contribute to immune evasion in the tumor immune microenvironment." (PMID 40963874, 2025). "In melanoma, Runx2 enhances tumor invasion and metastasis via the PI3K/AKT signaling pathway." (PMID 39595568, 2024). "Among the top features were also other fibroblast-associated TF like SP7, RUNX2, and DLX5, which could suggest CAF-mediated collagen production at the tumor site." (PMID 39161957, 2024). "These database findings corroborate the dual prognostic implications of RUNX1, underline the primary negative prognostic influence of RUNX2, and validate the tumor-suppressive role of RUNX3." (PMID 38430423, 2024).